CXCL10 (C-X-C motif chemokine ligand 10)
Diseases named in the same sentence as CXCL10 in open-access papers (continued):
Sharing a sentence is not in itself a finding about the gene and the disease.
pancreatic cancer (continued). "Our research offers compelling evidence supporting the potential of CXCL10 as a viable target for clinical diagnosis and treatment of pancreatic cancer." (PMID 40129528, 2025). "We recently demonstrated that the RGD fiber-modified OBP-301 variant (OBP-502) induces the secretion of pro-inflammatory chemokines, CCL5 and CXCL10, from murine colorectal and pancreatic cancer cells." (PMID 39108499, 2024). "A study by L. Gorchs and colleagues showed that CAFs down-regulate the expression of CXCR3 and CCR5 while upregulating CXCR4 expression in both 2D and 3D pancreatic tumor cultures, thereby inhibiting T cell tumor infiltration towards CXCL10." (PMID 39596815, 2024). "Expression of IL33 and other IRF3 target genes, TNF, IL1B, and CXCL10, were highly upregulated in pancreatic cancer compared to the normal pancreas in a large collection of samples represented in TCGA and GTEx databases." (PMID 38816352, 2024). "Nab-PTX treatment increases CXCL-10 expression in pancreatic cancer cells leading to reduced secretion of CAF-derived IL-6 subsequently impairing cancer migration and invasion." (PMID 37480115, 2023). "The expression of CXCL10 in normal tissues and pancreatic cancer tissues were compared based on TCGA databases." (PMID 36782176, 2023). "The antitumor efficacy of parvovirus vectoring cyto/chemokines (IL-2, MCP-3/CCL7 and IP-10/CXCL10) was assessed in pancreatic cancer xenograft." (PMID 35686109, 2022). "The CXCR3 ligands CXCL9 and CXCL10 have been suggested to promote an anticancer immune response in several types of solid tumor, but their role in pancreatic cancer is still controversial." (PMID 35954489, 2022). "The CXCR4/CXCL12 axis seems to play an important role in the desmoplastic reaction characterizing PDAC, while CXCR3/CXCL10 resulted expressed in pancreatic tumor tissue, and their presence has been correlated with poor prognosis." (PMID 36142575, 2022). "Nab‐paclitaxel can block pancreatic cancer cell migration and invasion effects by increasing CXCL10 expression in cancer cells and inhibiting IL-6 expression in CAF cells." (PMID 35468838, 2022). "In contrast, in pancreatic cancer, expression of both CXCL10 and CXCR3 in tumor tissue has been correlated with a poor prognosis mostly due to increased chemoresistance." (PMID 34328416, 2021). "To identified the main source of CXCL10, we downloaded an available human pancreatic cancer single-cell RNA-sequencing (scRNA-seq) data from the Genome Sequence Archive in the BIG Data Center, Chinese Academy of Sciences under accession code CRA00116010." (PMID 34276760, 2021). "In this study, we delineate the importance of CXCL10/CXCR3 signaling during the early phase of pancreatic cancer development." (PMID 34328416, 2021). "In pancreatic cancer, both CXCL10 and CXCR3 are expressed in tumor tissue, and their presence has been correlated with poor prognosis." (PMID 34328416, 2021). "The expression level of CXCL10 in pancreatic cancer tissue was higher than that in normal pancreatic tissue, and high expression level of CXCL10 was correlated with shorter overall survival." (PMID 34276760, 2021). "Here, we delineate the importance of CXCL10/CXCR3 signaling during the early phase of murine pancreatic cancer." (PMID 34328416, 2021). "For instance, PSCs recruit Tregs via the IP-10/CXCL10 pathway, and IP-10 is elevated in pancreatic cancer patients, which is associated with a high stroma content and a decreased median overall survival." (PMID 30060755, 2018). "CXCL10 could facilitate the metastasis of pancreatic cancer cells by modulating macrophage polarization." (PMID 40129528, 2025). "CXCL10 demonstrates significant potential as a therapeutic target in cancer treatment, warranting further investigation in the future diagnosis and management of pancreatic cancer." (PMID 40129528, 2025). "Univariate and multivariate Cox analyses demonstrated that CXCL10 may serve as an independent prognostic factor for pancreatic cancer." (PMID 40129528, 2025).
pancreatic cancer (continued). "Previous studies have not demonstrated a causal relationship between CXCL10 and pancreatic cancer progression." (PMID 40129528, 2025). "Reportedly, elevated CXCL10 expression correlates with poor prognosis in pancreatic cancer; however, the mechanisms remain unclear." (PMID 40129528, 2025). "Univariate and multivariate Cox analyses revealed that CXCL10 may be an independent prognostic factor for pancreatic cancer compared to variables such as the patient’s gender, age, and tumor node metastasis stage and grade." (PMID 40129528, 2025). "Flow cytometry and co-culture experiments demonstrated that CXCL10 could promote the migration of pancreatic cancer cells by inducing M2 polarization of macrophages." (PMID 40129528, 2025). "CXCL10 demonstrates potential as a therapeutic target for managing pancreatic cancer." (PMID 40129528, 2025). "CXCL10 and CXCL11 were highly expressed in pancreatic cancer and associated with poor prognosis of patients through cell adhesion molecules chemokine signaling, cytokine-cytokine receptor interaction, natural killer cell-mediated cytotoxicity, and Toll-like receptor signaling pathways." (PMID 40129606, 2025). "We found increased M1-like macrophage accumulation in estrogen-depleted mice, where elevated CXCL10 and CCL2 levels were observed, consistent with findings in a pancreatic cancer model where CXCL10/CXCR3 signaling was shown to maintain macrophages in the pro-inflammatory M1 phenotype." (PMID 39007345, 2024). "The levels of CXCL10 and CCL21 were associated with pain in pancreatic cancer patients." (PMID 35468838, 2022). "Thus, even though CXCL10 has an important effect on pancreatic cancer, new multimodal therapeutic approaches need to be explored." (PMID 35493517, 2022). "However, it needs to be noted that in pancreatic cancer expression of both CXCL10 and CXCR3 in tumor tissue have been correlated with metastasis and poor prognosis." (PMID 34328416, 2021). "However, since tissue-resident macrophages have been attributed important roles in established pancreatic cancer, we also determined if this population can be the recipients for CXCL10." (PMID 34328416, 2021). "The role of CXCL10 in pancreatic cancers seems clear, while that of CXCL9 remains undefined." (PMID 31913856, 2020). "It is hypothesized that that pancreatic cancer cells induce stromal expression of CXCL10 in PDAC that contributes to an immunosuppressive and tumour-promoting microenvironment." (PMID 31415645, 2019). "Consequently, we hypothesize that CXCL10 may facilitate the progression of pancreatic cancer by inducing macrophage polarization towards the M2 phenotype through the upregulation of VEGFA." (PMID 40129528, 2025). "Various statistical methods, including inverse-variance weighted, MR–Egger, weighted median, and simple and weighted mode, indicated that there might not be a direct causal relationship between CXCL10 expression and pancreatic cancer." (PMID 40129528, 2025). "Consequently, we investigated whether CXCL10 affects the progression of pancreatic cancer by regulating immune cells." (PMID 40129528, 2025). "However, the precise mechanisms by which CXCL10 regulates VEGFA expression in pancreatic cancer remain unclear, necessitating further investigation in subsequent studies." (PMID 40129528, 2025). "Accordingly, CXCL10 may be used as an independent prognostic indicator for pancreatic cancer." (PMID 40129528, 2025). "Akin to the findings in the pancreatic cancer trial that was conducted with the same adenoviral vector, in this study involving recurrent prostate cancer we observed similar trends in cytokine concentrations i.e., increase in serum IL-12, IFNγ and CXCL10 with increased adenoviral doses." (PMID 37713401, 2023). "Our study demonstrates that CXCL10 and CXCL11 are novel biomarkers of TME and immune cell infiltration in pancreatic cancer by affecting the distribution of immune cells." (PMID 40129606, 2025).
pancreatic cancer (continued). "Most importantly, our study explored the mechanism of action of CXCL10 and CXCL11 in the TME and immune cell infiltration of PAAD and provided information anticipated to facilitate pancreatic cancer immunotherapy." (PMID 40129606, 2025). "To further explore the important role of CXCL10 and CXCL11 in pancreatic cancer, we analyzed the related signaling pathways involving CXCL10 and CXCL11 through GSEA." (PMID 40129606, 2025). "Subsequently, we evaluated the DEGs related to the immune score and the stromal score and determined the prognosis-related genes from the clinicopathological data, and we identified CXCL10 and CXCL11 as prognostic factors in the pancreatic cancer TME." (PMID 40129606, 2025). "Doses of at least 4 Gy induced module 1 (e.g., CCL5, CXCL10) and module 4 (e.g., CCL20, CXCL8) chemokines in pancreatic cancer cells, with larger effects using higher radiation doses." (PMID 40811032, 2025). "Most importantly, the GEO databases (GES71729), GEPIA, TISIDB, TIMER databases PAAD cohort were used to verify our results, the expression levels of CXCL10 and CXCL11 in pancreatic cancer and normal pancreatic epithelial cells were verified by RT-PCR." (PMID 40129606, 2025). "The results showed that the expression of CXCL10 and CXCL11 was significantly increased in pancreatic cancer, and CXCL10 was statistically significant." (PMID 40129606, 2025). "Nevertheless, our research confirmed that CXCL10 and CXCL11 are important genes for the prognostic evaluation of pancreatic cancer." (PMID 40129606, 2025). "For further validation, we used GEPIA and GEO databases (GES71729) to verify the expression of CXCL10 and CXCL11 in pancreatic cancer and their relationship with the prognosis of patients." (PMID 40129606, 2025). "In summary, we have identified CXCL10 and CXCL11 as key genes affecting the prognosis and immune infiltration of pancreatic cancer." (PMID 40129606, 2025). "CXCL9, CXCL10 and CXCL11 have been previously shown to be effective in supporting an adequate antitumoral response in various cancers, although results in pancreatic cancer have been conflicting." (PMID 39885986, 2024). "Expression of both CXCL10 and CXCR3 in tumor tissue has been correlated with a poor prognosis in pancreatic cancer." (PMID 35493517, 2022). "Previously, Ym1+ macrophages in the KC animal model have been shown to drive fibrosis during pancreatic cancer development, and after neutralization of CXCR3, or alternatively neutralization of CXCL10, we observed a correlating increase in fibrosis." (PMID 34328416, 2021). "The CXC ligand family (CXCL5, CXCL9, CXCL10, CXCL11, and CXCL17) plays a vital role in regulating pancreatic cancer progression." (PMID 33393862, 2021). "Then we analyzed the RNA expression of CXCL10 and its receptor CXCR3 at single-cell level in pancreatic cancer." (PMID 34276760, 2021). "Recently, CXCL10 and CCL21 are demonstrated to promote migration of pancreatic cancer cells toward sensory neurons and increase the frequency of cancer-associated pain." (PMID 33681290, 2021). "Led by our mouse data, we stratified pancreatic cancer patients from The Cancer Genome Atlas (TCGA) dataset according to a designed gene list based on classical MDSC markers, including ITGAM (CD11b) and CXCL10." (PMID 31940491, 2020). "CXCL10 and CXCL11 may be new targets for molecular targeted therapy and immunotherapy of pancreatic cancer." (PMID 40129606, 2025). "The results of the PPI network and Cox regression analyses showed that CXCL10 and CXCL11 are valuable factors involved in the TME of pancreatic cancer and are correlated with the prognosis and clinicopathological characteristics of pancreatic cancer patients." (PMID 40129606, 2025). "Finally, the molecular mechanism by which CXCL10 and CXCL11 are involved in immune cell infiltration in pancreatic cancer was analyzed, and these results are anticipated to facilitate pancreatic cancer immunotherapy." (PMID 40129606, 2025).
pancreatic cancer (continued). "Recent studies have explored the role of CXCL10 and CXCL11 in pancreatic cancer." (PMID 40129606, 2025). "In addition, we revealed the relationship of CXCL10 and CXCL11 in immune cell infiltration landscape of pancreatic cancer." (PMID 40129606, 2025). "Our findings indicate that CXCL10 and CXCL11 may be new targets for pancreatic cancer immunotherapy." (PMID 40129606, 2025). "Previous reports showed that CXCL9, CXCL10, and CCL5 could mark T cell–inflamed phenotype of pancreatic cancer." (PMID 35692828, 2022). "Taken together these data suggest no significant role for T cells in CXCL10/CXCR3-driven development of pancreatic cancer." (PMID 34328416, 2021). "Our data also suggest that the ligands for the chemokine receptors CXCR3 (CXCL9, CXCL10, CXCL11) and CCR5 (CCL8) might affect the spatial distribution of CD8+ T cells in human pancreatic tumor tissues and enhance the relative T cell trafficking into tumor rich areas." (PMID 35954489, 2022). "Notably, the T cell chemokine attractants CCL5, CXCL9 and CXCL10 were increased in DMXAA-treated tumors, macrophages and DCs, as well as KPC1242 epithelial tumor cells, suggesting that these chemokines could participate in the recruitment of T cells to STING agonist-treated pancreatic tumors." (PMID 31036082, 2019).
Hepatitis (47 papers, 2012 to 2025). Inflammation of the liver. "Acute hepatitis A caused by hepatitis A virus infection is associated with the production of chemokines such as CXCL10, which is directly activated by IRF3." (PMID 36673407, 2023). "Plus, additional chemokines, CXCL-9 and CXCL-10, were higher in men and have been associated with liver inflammation." (PMID 35493503, 2022). "We further documented that deficiency or blockade of CXCL10 attenuated the development of Con A-induced hepatitis associated with reduction of the infiltrating monocytes, especially inflammatory Ly6Chi monocytes." (PMID 32641985, 2020). "CXCL10 neutralizing antibody and CXCL10 deficient mouse were used to study the role of CXCL10 in immune cell migration and pathogenesis of Con A-induced hepatitis." (PMID 32641985, 2020). "Baseline CXCL10 serum concentration is linked to the outcome of antiviral therapy in monoinfected hepatitis patients, as well as in patients coinfected with HIV." (PMID 24692853, 2014). "From Jensen lab: Arthritis, Cryoglobulinemia, and Hepatitis are associated with the gene CXCL10." (PMID 39766770, 2024). "Hepatitis A virus infection can increase the production of CXCL10 by RIG-I-like receptor signal molecules." (PMID 41180231, 2025). "Here, we found that IPA and IAA administration significantly reduced the severity of WD-induced liver inflammation, as indicated by the mRNA levels of Tnf-α and Cxcl10." (PMID 38299316, 2024). "Elevated serum levels of CXCL10 are described in patients with AIH in correspondence with liver inflammation, primary biliary cirrhosis (PBC), chronic viral hepatitis, mixed cryoglobulinemia and autoimmune thyroiditis." (PMID 37108648, 2023). "Apart from our studies and findings, a prior comprehensive review indicated enhanced expression of Th1 phenotypic cytokines (IL-2 and IFN-γ), and high serum levels of IFN-γ inducible chemokines CXCL-9 and CXCL-10 during the process of hepatitis flare." (PMID 35163330, 2022). "High serum IFN-γ inducible chemokines CXCL-9 and CXCL-10 levels were also found to correlate with the development of hepatitis flares." (PMID 35163330, 2022). "CXCL10 is chemokine shown to promote T cell adhesion to endothelial cells and when expressed by Kupffer cells, contributes to ConA-induced hepatitis." (PMID 35720411, 2022). "Clear parallels from our study can be drawn with other infections, for example, the expression of CXCL10 was IFN independent – an observation also made with Hepatitis A infection." (PMID 33912186, 2021). "Our data also indicates that the interplay between KCs and monocytes via CXCL10 contributes to Con A-induced hepatitis." (PMID 32641985, 2020). "Among the reduced chemokines, we have identified CXCL10 as a key chemokine to participate in recruiting inflammatory monocytes during Con A-induced hepatitis." (PMID 32641985, 2020). "In contrast, our studies reported here show that both inhibiting CXCL10 activity and knocking out CXCL10 function specifically reduce the infiltrating inflammatory monocytes, thereby leading to attenuating Con A-induced hepatitis." (PMID 32641985, 2020). "Our data indicate that the interplay between KCs and infiltrated monocytes via CXCL10 contribute to Con A-induced hepatitis." (PMID 32641985, 2020). "The most pronounced difference among all investigated SIM was observed for CXCL10 concentrations with highest levels in patients with hepatitis." (PMID 31575964, 2019). "Intrahepatic and peripheral levels of CXCL10 are elevated in HCV-infectedpatients with high levels of liver inflammation and fibrosis." (PMID 28636655, 2017). "The mRNA expression of inflammatory CXCL9 and CXCL10 was significantly increased 3 h after induction of hepatitis, a time point well before liver damage became detectable by plasma ALT levels." (PMID 26052942, 2015). "We quantified the fraction of hepatic CD4+ T cells expressing CXCR3, the receptor for CXCL9 and CXCL10 that were strongly up-regulated at an early stage of Con A-induced hepatitis." (PMID 26052942, 2015).
Hepatitis (continued). "CXCL9 and CXCL10 mRNA expression decreased over time whereas CXCL12 recovered to its initial levels within 24 h after hepatitis induction." (PMID 26052942, 2015). "Taken together, our study indicated that salidroside pretreatment ameliorates Con A-induced hepatitis and suggested that infiltrated T lymphocytes modulated by CXCL-10 and NF-κB signaling pathway served to attenuate the inflammatory response." (PMID 24808635, 2014). "CXCL9 (monokine induced by IFN-γ [MIG]) and IP-10 (IFN-γ-inducible protein 10, also called CXCL10) have been reported to play important roles during hepatitis flares in CHB." (PMID 24124595, 2013). "Bleomycin did not alter the T cell cytokine milieu in CXCL10-/- mice, weakening the support for the idea that CXCL10 might limit fibrosis by skewing T cell polarization to the Th1 phenotype as demonstrated in hepatitis models." (PMID 33145014, 2020). "Taken together, CXCL-10 expression may contribute to accumulation of T lymphocytes and subsequent liver injury in Con A-induced hepatitis." (PMID 24808635, 2014). "Similarly, the pro-inflammatory chemokine CXCL10 has been consistently reported as upregulated in the CNS in response to infection with neurotropic viruses like herpes, HIV-1, hepatitis, and West Nile virus." (PMID 40985448, 2025). "Conversely, other ISGs, including ISG20, IFI16, APOBEC3G, CXCL10, and CXCL11, which were predominantly expressed in T cells and nMacs, and upregulated during the hepatitis phase, showed a positive correlation with serum ALT levels, indicating their involvement in liver injury." (PMID 39135698, 2024). "Activation of STING was associated with an aggravated expression of several inflammatory cytokines, including IL-18, IL-6, IL-1β, TNFα, and C-X-C motif chemokine ligand 10 (CXCL-10) in HFD-induced NAFLD mice, whereas repressing STING signaling attenuated lipid accumulation and liver inflammation." (PMID 33924165, 2021). "Significantly lower CXCL10 concentrations were documented in patients without hepatitis in the EPI- (2.04 ± 0.36 log10pg/mL; p < 0.001), ENI- (1.98 ± 0.32 log10pg/mL; p < 0.001) or ENI-HR-phase (2.08 ± p0.19 log10pg/mL; p < 0.001)." (PMID 31575964, 2019). "In ConA-induced hepatitis, the expression of chemokines and adhesion molecules were demonstrated to play important roles in recruiting lymphocytes into the liver to aggravate liver injury, such as MIP-1α, CXCL10, and ICAM-1." (PMID 28377718, 2017).